STRAP (serine/threonine kinase receptor associated protein)
Diseases named in the same sentence as STRAP in open-access papers (continued):
Sharing a sentence is not in itself a finding about the gene and the disease.
glioblastoma (2 papers, 2020 to 2023). The most malignant astrocytic tumor (WHO grade IV). "These include, to name a few, G-protein beta-3 subunit splice variant in hypertension, mutation in AAAS protein causing Triple-A syndrome, and the role of WD11 and STRAP proteins in glioblastoma and carcinogenesis." (PMID 36979349, 2023).
intestinal cancer (2 papers, 2024 to 2025). "Although STRAP is crucial for embryonic stem cell differentiation and development through alternate splicing, its upregulation maintains intestinal cancer cell stemness, leading to tumorigenic functions." (PMID 40558481, 2025). "As an upstream regulator of MEK/ERK and Wnt/β-Catenin signaling in intestinal cancers, STRAP plays an important role in promoting APC-induced tumor development and progression." (PMID 40558481, 2025).
osteosarcoma (2 papers, 2021 to 2025). A usually aggressive malignant bone-forming mesenchymal neoplasm, predominantly affecting adolescents and young adults. "STRAP silencing in these osteosarcoma cells resulted in inhibited invasion, migration, and re-implantation." (PMID 40558481, 2025). "STRAP siRNA knockdown decreased migration and invasion of osteosarcoma cells." (PMID 34206917, 2021). "STRAP is overexpressed in several malignancies including another pediatric cancer, osteosarcoma." (PMID 34206917, 2021).
Parkinson disease (2 papers, 2020 to 2024). A progressive degenerative disorder of the central nervous system characterized by loss of dopamine producing neurons in the substantia nigra and the presence of Lewy bodies in the substantia nigra and locus coeruleus.
anemia (1 paper, 2020). A reduction in the number of red blood cells, the amount of hemoglobin, and/or the volume of packed red blood cells. "In addition, previous studies demonstrated that U2AF1 mutant is prone to anemia and thrombocytopenia, and S34F mutant of U2AF121 can have reduced erythropoiesis and abnormal granulo-monocyte differentiation via regulating the downstream target gene H2AFY and STRAP to form abnormal splicing." (PMID 33122737, 2020).
atrial fibrillation (1 paper, 2025). A disorder characterized by an electrocardiographic finding of a supraventricular arrhythmia characterized by the replacement of consistent P waves by rapid oscillations or fibrillatory waves that vary in size, shape and timing and are accompanied by an irregular ventricular response. "This study aimed to elucidate the role of the deubiquitinase USP38 in chronic kidney disease (CKD)-associated atrial fibrillation (AF) by investigating its impact on atrial structural and electrical remodeling and its interaction with STRAP and TGF-β/SMAD signaling." (PMID 40514673, 2025).
colon adenoma (1 paper, 2025). An adenoma that arises from the colon. "STRAP has been shown to be upregulated in more than 50% of colon adenomas, and the inactivation of APC or the activation of Wnt/ß-Catenin signaling increases the expression of STRAP." (PMID 40558481, 2025).
colorectal adenocarcinoma (1 paper, 2018). The most common type of colorectal carcinoma. "Importantly, we found that STRAP and MELK were overexpressed and highly phosphorylated in colorectal adenocarcinomas and their expression were significantly correlated with tumor stages." (PMID 29783958, 2018).
colorectal adenoma (1 paper, 2016). An adenoma that arises from the colon or rectum. "These, coupled with the finding that STRAP is also upregulated in 50.8% colorectal adenomas, indicate that both STRAP and β-catenin function in the early stage of CRC." (PMID 26910283, 2016).
lung adenocarcinoma (1 paper, 2018). A carcinoma that arises from the lung and is characterized by the presence of malignant glandular epithelial cells. "Analysis of clinical data from the cancer genome atlas reveals that the level of STRAP mRNA expression is upregulated in lung adenocarcinoma with metastasis, strongly implying that STRAP participates in the pathology of lung adenocarcinoma metastasis." (PMID 29849900, 2018).
lymph node metastasis (1 paper, 2018). "Furthermore, the expression of MELK, but not STRAP, was associated with lymph node metastasis." (PMID 29783958, 2018).
melanoma (1 paper, 2014). A malignant, usually aggressive tumor composed of atypical, neoplastic melanocytes. "Four of the proteins with increased levels in highly metastatic melanoma cells were also seen in our study: Vimentin and TIM levels decreased after proton beam treatment, and STRAP and Actinin 4 increased." (PMID 24392146, 2014).
non-small cell lung carcinoma (1 paper, 2025). A group of at least three distinct histological types of lung cancer, including non-small cell squamous cell carcinoma, adenocarcinoma, and large cell carcinoma. "STRAP interacts with Notch3 and stabilizes it by inhibiting its proteasomal degradation, and they are co-upregulated in non-small cell lung carcinoma." (PMID 40558481, 2025). "The upregulation of STRAP correlates with ICN3 (intracellular fragment of Notch3) in 59% of non-small-cell lung cancers and increases its stabilization." (PMID 40558481, 2025).
ovarian tumor (1 paper, 2024). "The role of genes encoding such proteins, LUC7L2, MRPL46, MRPL14, PARP4, STRAP, and PAPOLA, in ovarian tumor development has already been investigated in the literature." (PMID 39456618, 2024).
pancreatic cancer (1 paper, 2020). "Based on this, we successfully constructed STRAP-interfering pancreatic cancer cell lines with STRAP shRNA lentivirus, and verified their effects in vitro and in vivo." (PMID 33134183, 2020).
viral infection (1 paper, 2024). "To further study the effects of STRAP KO on viral infection, we generated single-cell clones that showed undetectable levels of STRAP by immunoblot, and two were selected for further assays." (PMID 38617272, 2024). "While STRAP KO cells produced fewer infectious virions, the mechanism by which STRAP was modulating viral infection remained unclear." (PMID 38617272, 2024).
tumor (23 papers, 2014 to 2026). "The hypoxic tumor microenvironment reduces FTO protein expression by increasing serine/threonine kinase receptor-associated protein (STRAP)-mediated ubiquitination and facilitates CRC metastasis." (PMID 37391814, 2023). "Serine-threonine kinase receptor associated protein (STRAP) is upregulated in several malignancies and plays an important role in tumor growth and metastasis." (PMID 34206917, 2021). "We were also interested in genes associated with promoting tumor growth and found several that were downregulated in the AS STRAP KO cells, notably platelet-derived growth factor receptor ß (PDGFRβ)." (PMID 34206917, 2021). "TRINGS binds STRAP (serine–threonine kinase receptor-associated protein) and inhibits STRAP-GSK3β-NF-κB necrotic signaling to protect tumor cells from cell death." (PMID 33558499, 2021). "STRAP is considered a prognostic factor due to the association between tumor stage and the protein levels." (PMID 32527012, 2020). "On the contrary, circPCNXL2 (hsa_circ_0016956) is overexpressed in iCCA and promotes tumor cell proliferation and metastasis by interacting with serine-threonine kinase receptor-associated protein (STRAP) and, consequently, facilitating the activation of MEK1/2-ERK1/2." (PMID 40723336, 2025). "The tumor-suppressive role of STRAP during tumorigenesis (if any) should be tested using in vivo genetic experiments and human tumor specimens." (PMID 40558481, 2025). "CRISPR/Cas9 knockout studies in HCC cell lines Huh6 and Huh demonstrate that STRAP supports cell proliferation and tumor growth by amplifying β-Catenin signaling activity." (PMID 40558481, 2025). "STRAP silencing showed the reduced expression of Notch receptors and its target genes, potentiated chemotherapeutic efficacy, and showed the inhibition of tumor growth in vitro and in vivo." (PMID 40558481, 2025). "In summary, our study reveals that circPCNXL2 is upregulated in ICC and plays a tumor promoter in ICC development by interacting with STRAP to promote the phosphorylation of ERK." (PMID 38365721, 2024). "LncRNA TRINGS can blind STRAP and control the STRAP-GSK3β-NF-κB necrotic pathway to rescue tumor cells." (PMID 37934582, 2023). "TRINGS promotes tumour growth (in vitro and in vivo) via binding to STRAP and inhibits the STRAP-GSK3β-NF-κB necrotic pathway." (PMID 36230680, 2022). "STRAP knockdown and knockout cells were examined for phenotypic alterations in vitro and tumor growth in vivo." (PMID 34206917, 2021). "On the other hand, TRINGS binds to STRAP and inhibits the STRAP–GSK3β–NF-κB necrotic signaling protecting tumor cells from death." (PMID 34298698, 2021). "Animals with AS STRAP KO tumors had significantly decreased relative tumor growth and mean tumor volume compared to those with AS WT tumors." (PMID 34206917, 2021). "Investigators began to study the role of STRAP in cancer when they found that STRAP inhibited the tumor suppressor, TGF-β." (PMID 34206917, 2021). "TRINGS facilitates tumor growth in vitro and in vivo by binding to STRAP and inhibiting STRAP-GSK3β-NF-κB necrotic pathway." (PMID 32174794, 2020). "Sanguinarine shows efficacious anti-tumor effects through downregulating and dephosphorelating STRAP and MELK." (PMID 29783958, 2018). "The expression and association between STRAP and MELK were also attenuated by sanguinarine in the tumor tissues." (PMID 29783958, 2018). "Nm23-H1, a tumor suppressor, enhances the STRAP-induced inhibition of TGF-β signaling via a redox-dependent interaction with STRAP." (PMID 29849900, 2018).
tumor (continued). "When baited with MELK, immunoprecipitated STRAP were significantly reduced both in sanguinarine and cisplatin treated tumor tissues extracts." (PMID 29783958, 2018). "Mounting evidence indicates that STRAP can promote tumor progression by inhibiting apoptosis and activating cell proliferation." (PMID 29849900, 2018). "STRAP promotes tumor progression through the inhibition of apoptosis and the activation of cell survival." (PMID 29849900, 2018). "From this study it is difficult to distinguish the effect of STRAP on tumor growth and metastasis in vivo." (PMID 26910283, 2016). "When compared with the vector control cells, downregulation of STRAP remarkably inhibited tumor growth in syngeneic mice." (PMID 26910283, 2016). "The combination of STRAP protein biology with tumor ecology may allow for the discovery of novel therapeutic targets that can disrupt the cancer ecosystem." (PMID 40558481, 2025). "In these malignancies, STRAP enhanced cancer cell proliferation and tumor growth." (PMID 34206917, 2021). "In vivo, STRAP knockout cells formed tumors less readily than wild-type tumor cells." (PMID 34206917, 2021). "Other investigators have examined STRAP knockdown and its effects on in vivo tumor growth." (PMID 34206917, 2021). "Further analysis of the genes FABP7 and STRAP in GSCs compared to tumor tissue may be especially efficacious." (PMID 32634135, 2020). "In addition, STRAP inhibits Sp1-dependent transcription, resulting in the downregulation of the tumor suppressor genes E-cadherin and p21Cip1, thereby promoting tumor progression in non-small-cell lung cancers." (PMID 29849900, 2018). "Both MELK and STRAP were significantly correlated with tumor stages." (PMID 29783958, 2018). "Therefore, the increased expression of STRAP in lung cancer contributes to the downregulation of E-cadherin and p21Cip1, which in turn leads to tumor progression." (PMID 29849900, 2018). "Overall, high level of STRAP expression in various cancers implies that STRAP has a role in tumor growth and aggressiveness, and therefore, inhibition of STRAP may be an attractive cancer therapeutic target." (PMID 29849900, 2018). "Besides, there is highly significant correlation between the expression of STRAP and β-catenin including its nuclear accumulation in these tumor samples (62.5% vs 41.3%)." (PMID 26910283, 2016). "This indicates that STRAP can promote tumor cell growth and invasion not only through Wnt/β-catenin pathway, but may also through regulating other signaling pathways, such as TGF-β signaling and MAPK pathway." (PMID 26910283, 2016). "However, the role of STRAP in tumor progression remains controversial." (PMID 32527012, 2020). "However, the exact nature of this mechanism is unknown, and further studies are needed to evaluate STRAP and Nm23-H1 activities during tumor progression." (PMID 29849900, 2018). "In addition to its biological roles, this review also focuses on the dual functions of STRAP in cancers displaying redox dysregulation, where it can behave as a tumor suppressor or an oncogene (i.e., it can either inhibit or promote tumor formation), depending on the cellular context." (PMID 29849900, 2018). "One study demonstrated that circPCNXL2 directly binds to serine-threonine kinase receptor-associated protein (STRAP) and induces the interaction between STRAP and MEK1/2, thereby promoting iCCA tumor progression through activation of the ERK/MAPK pathway." (PMID 41513616, 2026). "STRAP expression is significantly elevated in both human and mouse HCC tumor tissues compared to adjacent normal tissues, with its localization predominantly in the cytoplasm." (PMID 40558481, 2025). "Oncogenic STRAP inhibits E-cadherin and P21(CIP1) through modulation of transcription factor SP1, contributing to tumor progression." (PMID 36551208, 2022).
tumor (continued). "In the current study, we demonstrate STRAP inhibition with siRNA, shRNA, and CRISPR-Cas9 knockout (KO) decreased tumor cell viability, proliferation, growth, stemness, and motility in vitro and tumor growth in vivo." (PMID 34206917, 2021). "STRAP is markedly upregulated in non-small cell lung cancer (NSCLC) tissues and cell lines; however, functional knockdown of this protein significantly impairs cell migration, invasion, and tumor growth." (PMID 40558481, 2025). "In terms of the mechanisms, circPCNXL2 could directly bind to STRAP and induce the interaction between STRAP and MEK1/2, resulting in the tumor promotion in ICC by activation of ERK/MAPK pathways." (PMID 38365721, 2024). "The specific interactions between hypoxia, FTO, and STRAP are not elaborated and the effects of hypoxia tumor microenvironment on cellular m6A modification levels mediated by other m6A writers, erasers, and readers need further exploration." (PMID 34218271, 2021). "Furthermore, the overexpression of STRAP inhibits TGF-β-mediated growth suppression by increasing Smad7 binding to TGF-β receptors, which induces cell proliferation and tumor development." (PMID 29849900, 2018). "Downregulation of STRAP remarkably reduced primary tumor growth in ceca, in which no mice had lymph node metastasis, but all vector control mice had lymph node metastases and one mouse had liver metastasis." (PMID 26910283, 2016). "However, the tumor-suppressive effects of STRAP have not yet been confirmed, although the pro-apoptotic function of STRAP was observed in cancer cells." (PMID 32527012, 2020). "However, the tumor suppressive effects of STRAP have not yet been confirmed in cancer tissues, although the proapoptotic function of STRAP was observed in normal and cancer cells." (PMID 29849900, 2018).